TNF (tumor necrosis factor)
Diseases named in the same sentence as TNF in open-access papers (continued):
Sharing a sentence is not in itself a finding about the gene and the disease.
cancer (continued). "Cancer cachexia is regulated by proinflammatory cytokines such as interleukin-6 (IL-6), monocyte chemoattractant protein-1 (MCP-1), and tumor necrosis factor-α (TNF-α)." (PMID 24963216, 2014). "NFκB inhibition and anti-TNF therapy, together with the administration of IFN or TRAIL might offer an attractive combined strategy for immunomodulatory cancer therapy." (PMID 25132836, 2014). "TNF-α is involved in the regulation of a wide spectrum of biological processes including cell proliferation, differentiation, and apoptosis; blocking expression of TNF-α can reverse carcinoma progression." (PMID 25057912, 2014). "In previous cancer trials, the systemic toxicity of SEA was presumed to be related to TNF-α." (PMID 23964349, 2013). "Ovarian UT-OC-2 carcinoma cells had no NF-κB activation in respond to TNF whereas ovarian MDAH 2774 cancer cells induced TNF-activated NF-κB, indicating a critical role of NF-κB signaling on cell proliferation." (PMID 24376747, 2013). "Partly regulated by macrophage migration inhibitory factor (MIF), Th17 cells could produce higher levels of cytokines including TNF and IFN-γ, showing anti-cancer effect." (PMID 24386144, 2013). "Consequently, target cell-bound scFv:TNF can efficiently activate TNFR2 and thereby sensitize cancer cells to induction of TNFR1 apoptotic signaling." (PMID 23840967, 2013). "Although TNF-α has been evident of suppressing cancerous carcinoma, it also stimulates activation of NF-κB signaling via degradation of IκBα, leading to apoptosis resistance, as well as TNF-α resistance in cancer cells." (PMID 23573150, 2013). "However, the anticancer activities of AIMs were attenuated by TNF treatment, which suggests that the therapeutic efficacy of AIMs, if AIMs or meoru should apply to cancer patients, might be limited in the TNF high situation like the patients with far advanced cancer and cachexia." (PMID 23864892, 2013). "In cancer patients, inflammatory changes indicate that IDO may be induced by soluble factors including IFNγ, TNF-α, IL-1β, soluble CD40 ligand (sCD40L) and CTLA-4 ligation to CD80/CD86 expressed by DC." (PMID 24147117, 2013). "The hyperphosphorylation of Rb has been observed in many cancer cells, and it has been shown that high levels of TNF-α in cells results in Rb not working properly, but it has not been clear if faulty Rb also leads to the breakdown of skeletal muscle." (PMID 24302570, 2013). "IL-1β is also known to promote cancer progression by upregulating pro-metastatic genes such as matrix metalloproteinases and stimulate adjacent cells to produce angiogenic proteins or growth factors including VEGF, IL-8, IL-6, TNF-α and TGF-β." (PMID 23495140, 2013). "It has been reported that curcumin promoted tumor necrosis factor-α–induced apoptosis in a variety of cancer cells, but without a significant increase in the TNF-R1 expression level." (PMID 23663277, 2013). "HAMLET also triggered IL-6, IL-8, and TNF-α secretion in healthy, differentiated cells but not in carcinoma cells." (PMID 23505537, 2013). "Similarly, production of pro-inflammatory cytokines (IL-6, IL-8, IL-12p70, TNF-α and IL-1β) was strongly inhibited by TLR7 ligand in two cancer-derived HPV cell lines." (PMID 22513098, 2012). "Accordingly, the current study clarified that MBS extract induced the production of TNF-α and IFN-β from human cancer cells, and this led to the inhibition of the growth of these cells and this might lead to the death of treated human cancer cells." (PMID 23122182, 2012). "Tumor necrosis factor (TNF)-related apoptosis inducing ligand (TRAIL), a member of the TNF superfamily, interacts with its functional death receptors (DRs) and induces apoptosis in a wide range of cancer cell types." (PMID 22942679, 2012). "First, HMGB1 is acutely translocated and secreted by immune cells in response to TNF-α, IL-1β, or LPS stimulation, whereas cancer cells have no known stimuli for translocation and secretion." (PMID 22496788, 2012).
cancer (continued). "It has also been reported that BQ chewing contributed to the pathogenesis of cancer and OSF by impairing T cell activation and by induction of prostaglandin E2 (PGE2), TNF-α and IL-6 production, which affect oral mucosal inflammation and growth of oral fibroblasts/oral epithelial cells." (PMID 22912735, 2012). "A majority of cancer cells become resistant to TNF-α as a result of the activation of NF-κB and consequent induction of anti-apoptotic molecules (e.g. IAPs/Bcl-XL), as the pro-survival effects of TNF-α out-perform the pro-apoptotic effects." (PMID 21880146, 2011). "TNF-α and IFN-γ act against many other cancer cell lines as well." (PMID 22036896, 2011). "To determine whether a similar pattern of the effects of TNFα and CSE on NOD2 expression was seen in ileal biopsies we cultured biopsies obtained from otherwise healthy individuals undergoing cancer-screening endoscopy (n = 10) with CSE±TNFα." (PMID 21931826, 2011). "On the other hand, tumor necrosis factor alpha (TNF-α, cachectin), a potential mediator of cancer cachexia and the dysregulation of inflammation, increases the thermogenic activity of BAT and the rate of fatty acid synthesis from glucose in BAT assayed in vitro." (PMID 22182284, 2011). "Patients with a prior malignancy were insignificantly less frequently treated with anti-TNFα agents or anakinra at inclusion than patients without prior malignancy." (PMID 20064207, 2010). "Taking into account all malignancies, the number of observed cancers in patients exposed to anti-TNFα agents was non-significantly lower than the expected number from the general population (standardized incidence rate ratio: 0.75, 95% CI: 0.54 to 1.01)." (PMID 20064207, 2010). "Patients with prior malignancy are usually excluded from participation in RCTs and most clinical recommendations do not encourage treating these patients with anti-TNFα." (PMID 20064207, 2010). "Curcumin was likewise more effective in suppressing TNF-induced activation of NF-κB than DMC, BDMC and THC, whereas all curcuminoids inhibited growth of various cancer cell lines including T-cell leukemia (Jurkat), histiocytic leukemia (U937) and CML (KBM-5) to a similar extent." (PMID 20944521, 2010). "Indeed, our group has developed fully human fusion proteins based on the pro-inflammatory cytokines IL2 and TNF (L19-IL2; L19-TNF; F16-IL2) which are currently being investigated in phase I and in phase II clinical trials in patients with cancer." (PMID 19781067, 2009). "TNF-α has been shown to upregulate MMP-9 gene expression in malignant carcinoma via TNF-R1, and TNF-R1 but not TNF-R2 has been shown to be important in inflammatory responses involving IL-1β and MMP-3 and -9 in murine brain injury." (PMID 19435506, 2009). "We evaluated patients' bone homeostasis; we made peripheral blood mononuclear cell (PBMC) cultures to detect in vitro osteoclastogenesis; we dosed serum expression of molecules involved in cancer induced osteoclatogenesis, such as RANKL, OPG, TNF-alpha, DKK-1 and IL-7." (PMID 18978943, 2008). "Although TNF-α is not currently an anticancer agent for treatment of human cancers (because of side effects such as normal cell toxicity), low doses of TNF-α can markedly sensitize cancer cells to chemotherapy-induced apoptosis." (PMID 19087274, 2008). "HT-29 epithelial cancer cells were treated with 10 combinations of saturating or subsaturating concentrations of TNF, EGF and insulin (0, 0.2, 5, 100 ng/ml TNF and 0, 1, 100 ng/ml EGF or 0, 1, 5, 500 ng/ml insulin respectively), which collectively represent all the cues used in the study." (PMID 17559646, 2007). "IL-12 reached amaximum in CIN II and decreased in CIN III and carcinoma; but the differencesbetween groups were statistically not significant (K. W. test: P=.068 for IL-12 + p40,P=.264 for IFNγ, P=.077 for TNFα and P=.071 for IL-2)." (PMID 18288269, 2007).
cancer (continued). "Tumor Necrosis Factor (TNF)-Related Apoptosis-Inducing Ligand (TRAIL) selectively induces apoptosis in cancer cells but not in normal cells." (PMID 15916713, 2005). "As a proinflammatory cytokine, MIF counter-regulates the effects of glucocorticoids and stimulates the secretion of other cytokines such as tumor necrosis factor (TNF)-α and interleukin (IL)-1β, thus assuming a role in the pathogenesis of inflammatory, immune diseases and cancer." (PMID 16000172, 2005). "In cultured cancer cells that express RCAS1, RCAS1 is secreted into the medium RCAS1 is cleaved proteolytically by 12-O-tetradecanoylphorbol 13-acetate (TPA) as TNF-α and Fas-L are processed (manuscript in preparation)." (PMID 12888828, 2003). "In contrast to the large increases in plasma TNF observed in mice treated with DMXAA, plasma TNF levels in patients treated in a Cancer Research UK phase I trial were not elevated." (PMID 12085190, 2002). "Furthermore, ω-3 PUFAs have been shown to modulate inflammatory cytokines, notably interleukin-6 (IL-6) and tumor necrosis factor-α (TNF-α), both of which play pivotal roles in carcinogenesis and disease progression, supporting their potential therapeutic application in cancer management." (PMID 41515289, 2026). "Various inflammatory mediators such as tumor necrosis factor (TNF), which augments microvascular leakiness, along with interleukin-1 (IL-1) and interleukin-6 (IL-6), known to suppress albumin production, contribute to the observed decrease in serum albumin among cancer-afflicted individuals." (PMID 40034601, 2025). "Moreover, the contraindication of anti-TNF alpha agents—which remain a first-line treatment for chronic non-infectious uveitis—in cases of active cancer complicates therapeutic decision-making." (PMID 41003888, 2025). "This study aimed to investigate the potential anticancer effects of lercanidipine on cancer cell lines—particularly in combination with cisplatin—by assessing parameters such as cell viability (MTT assay), proliferation, MAPK pathway activity, caspase enzyme levels, and TNF-α expression." (PMID 40430470, 2025). "However, the fact that TNF-α correlations were largely absent in controls argues that any minor inflammatory state in controls did not reproduce the patterns seen in cancer patients." (PMID 40299527, 2025). "Adipocytes readily secrete pro-inflammatory adipokines, such as tumor necrosis factor-α (TNF-α), monocyte chemoattractant protein-1 (MCP-1), and interleukin-6 (IL-6), which recruit immune cells and amplify inflammatory processes, thereby promoting cancer development, progression, and metastasis." (PMID 40823082, 2025). "Cancer cells can reprogram astrocytes via the cyclic GMP-AMP synthase (cGAS)-Stimulator of Interferon Genes (STING) pathway by transferring 2′,3′-cyclic GMP-AMP (cGAMP), leading to the production of inflammatory cytokines such as interferon-α (IFN-α) and tumor necrosis factor-α (TNF-α)." (PMID 40136375, 2025). "Notably, TNF-α and IFN-γ synergize to activate GSDMD, GSDME, Caspases (-3/-7/-8), and MLKL, triggering PANoptosis across 13 human cancer cell lines (including colon, lung, melanoma, and leukemia), highlighting cytokine-driven PANoptosis as a therapeutic target." (PMID 40831559, 2025). "However, clinical studies employing anti-TNF-α antibodies in cancer patients with cachexia have failed to reverse muscle atrophy, suggesting the need for additional anti-inflammatory strategies." (PMID 40519290, 2025). "Although PTX3 engages commonly recognized signaling pathways, such as TNF-α, NF-κB, FGF, and PI3K/AKT, it can exert paradoxical effects in different cellular contexts, either promoting or inhibiting the proliferation, migration, invasion, and metastasis of cancer cells." (PMID 41479916, 2025).
cancer (continued). "Notably, chemokines like CXCL9, CXCL10, and CXCL11 are primarily produced by a variety of cell types, including monocytes, endothelial cells, fibroblasts, and cancer cells, in response to IFN-γ, and this response is further amplified by TNF-α, highlighting their role as pro-inflammatory cytokines." (PMID 40227454, 2025). "Interestingly, while AFP failed to correlate with TNF-α among cancer patients, it approached a moderate correlation (rho = 0.383, p = 0.0956) in controls, though still not significant." (PMID 40299527, 2025). "Human cancer cells treated with HDAC inhibitors, arsenic trioxide, TNF-α, IFN- γ, rapamycin, and antiestrogen hormonal therapy activate autophagy as a pro-survival strategy, suggesting that inhibiting autophagy might make cancer cells more sensitive to these treatments." (PMID 40248706, 2025). "Furthermore, the levels of multiple cytokines, including IL-2, IL-4, IL-6, IL-10, TNF, and IFN-γ in the supernatant of the OHSV2-DSTEFAP5/CD3 group co-cultured with cancer cells and fibroblasts, showed a significant increase compared to groups with either cell type alone." (PMID 40406146, 2025). "According to the results of GSEA in pan-cancer, NCBP2 was closely related to immune related pathways, such as IFN-alpha response, IFN-gamma response, IL-6/JAK/STAT3 signaling, IL-2/STAT5 signaling, allograft-rejection pathways, inflammatory response, and TNF alpha signaling-via NFKB." (PMID 40124611, 2025). "Through these gap junctions, cancer cells stimulate the cGAS-STING (stimulator of interferon genes) pathway in astrocytes via 2′,3′-cyclic GMP-AMP (cGAMP), increasing the production of potent inflammatory cytokines, such as interferon-α (IFN-α) and tumor necrosis factor." (PMID 39780275, 2025). "Furthermore, given PTX3’s pivotal role in inflammation and tissue repair, especially in bone remodeling, cancer patients with bone metastases may benefit from PTX3 inhibition, or even TNF-α inhibition, an area that warrants further exploration." (PMID 41479916, 2025). "Moreover, NK cell-induced death in cancer cells may be stimulated through death receptor-mediated apoptosis including TNF-related apoptosis-inducing ligand, Tumor Necrosis Factor (TNF), and Fas ligand." (PMID 40342534, 2025). "TNF-α is a key cytokine in the inflammatory response, essential for defending against infections, and IFN-γ is crucial in cell-mediated immunity, coordinating various antimicrobial functions, inducing antiviral responses, and exhibiting antiproliferative effects on cancer cells." (PMID 40362445, 2025). "Interestingly, following activity onset (CT38), pathways established to be involved in cancer-induced muscle wasting, including JAK-STAT, tumor necrosis factor (TNF), and FoxO signaling pathways, were enriched from genes increased in KPC mice (e.g., Jak3, Osmr, Nfkbia, Bcl3, Gadd45g, and Cebpb)." (PMID 40349340, 2025). "Shifting MCs toward a TNF+ rather than VEGF+ phenotype may also be beneficial in HPV-positive cancer treatment; however, this therapeutic strategy needs further investigation." (PMID 41465542, 2025). "Furthermore, the inhibitory effect of cancer patient sera on muscle differentiation was not reduced by the TNFα-neutralizing antibody." (PMID 40283883, 2025). "Additionally, several critical cancer-related pathways, including the phosphatidylinositol 3-kinase (PI3K)-Akt, FoxO, mitogen-activated protein kinase (MAPK), and tumor necrosis factor (TNF) signaling pathways, were identified as being regulated by the combination of IR808-ATIPA and radiation." (PMID 40831788, 2025).
cancer (continued). "Depending on the existing balance within the sphingolipid network of cancer cells/tissue, the activation of TNF-α/TNFR axis may result in either activation of proliferation (so-called TNF-α resistance mechanism) or apoptosis (traditional death-promoting pathway)." (PMID 38698424, 2024). "In this regard, the interaction of ligands of the TNF-α (Tumor Necrosis Factor-α) family (TNF-α, FasL, TRAIL) with their respective receptors, as well as of PD-L1 (Programmed Death Ligand-1) with its receptor PD1, have been shown to mediate the docking of EVs produced by different cancer cells." (PMID 38542421, 2024). "This targeting mechanism of ExoDS may be attributed to a variety of membrane receptors like integrin α and β chains (αMβ2), ICAM-1, MFG-E8, TNF, FasL, CD86, CD80, CD40, CD83, MHC-I, MHC-II, NKG2D, IL-15Rα, CD21, CD11c, and CCR7, which help mDC-derived exosomes identify cancer cells." (PMID 38903193, 2024). "Additionally, these Th1 cells could directly impede cancer cell proliferation by secreting IFN-γ and TNF." (PMID 38041687, 2024). "However, decreased TNF-alpha limits NK cell infiltration into the TME, reduces their cytotoxic potential, and disrupts the balance between activating and inhibitory molecules, thereby indirectly facilitating cancer progression." (PMID 39518143, 2024). "In parallel with considerable overproduction of other pro-inflammatory modulators, such as TNFα, IL-2, IL-6, MIG (CXCL9), MIP-1β (CCL4) and MIP-2 (CXCL2), we also detected a significantly lower secretion of IL-10 by tILC2s that contradicted the conventional ILC2 role in cancer." (PMID 38524132, 2024). "Thus, targeted delivery of TNF through an inactive adoptive cell in combination with an IAP antagonist could be a novel approach to treat cancers while obviating the severe side effects from both classical ACT therapy and the systemic administration of TNFα." (PMID 39105847, 2024). "ASTX660 has been found to have no cytotoxic effects on three mouse cancer lines—MOC1, MOC2, and MEER (a model developed to express E6 and E7 HPV proteins)—and in combination with TNFα caused an increase in the surface expression of CRT/HSP70 only in the MOC1 line." (PMID 39458950, 2024). "In cancer, the corresponding signal transduction after PRR stimulation amplifies the effect of the immunosuppressive response of MDSCs by producing a variety of proteins, including arginase-1, iNOS, IDO-1, prostaglandin E2, PD-L1, CD40, TNF-α, IL-1β, IL-6, cyclooxygenase-2, and others." (PMID 39035356, 2024). "Enhanced levels of intracellular cytokines, such as interleukin 2(IL2), TNF-α, interferon-gamma (IFN-γ), and IL6, were observed within the memory subpopulation, indicating that IL7 may stimulate a memory immune response targeting cancer." (PMID 38289597, 2024). "However, clinical trials that evaluated the efficacy of anti-TNF therapies failed to prevent muscle atrophy in patients with advanced cancer cachexia." (PMID 39456555, 2024). "Like other cytotoxic cancer therapies, immunotherapy promotes inflammation within the TME, which can include cytokine release syndrome characterized by hypersecretion of pro-inflammatory cytokines, including IL-6, IL-1, TNFα, IL-5, IL-10, IFN, and TGFs by various immune cells." (PMID 38330013, 2024). "However, there is a lack of specific data regarding different cancer types and the optimal timing of TNF inhibitors treatment." (PMID 39272800, 2024). "In addition, we found that REEP4 was primarily enriched in cancer-related cell signal pathways such as the cell cycle, MAPK signaling pathway, HIF-1 signaling pathway, NOD-like receptor signaling pathway, TNF signaling pathway, etc., through KEGG signal pathway analysis." (PMID 38552216, 2024).